IRF3 (interferon regulatory factor 3)
Diseases named in the same sentence as IRF3 in open-access papers (continued):
Sharing a sentence is not in itself a finding about the gene and the disease.
viral infection (continued). "However, whether the SARS-CoV-2 M protein affects IRF3 phosphorylation in an in vivo viral infection is unknown, but this knowledge may contribute to our understanding of the role of the SARS-CoV-2 M protein in SARS-CoV-2 infection." (PMID 33372174, 2020). "However, we cannot exclude that virus infection leads to a direct Mx2 induction through IRF3 activation implying that the converter system may be triggered independently of IFNAR signaling." (PMID 33137201, 2020). "In addition, the interaction between DDX56 and IRF3 increased during viral infection." (PMID 31340999, 2019). "Interestingly, TRAF6 was also able to activate IRF3 and induce IFNs during viral infection." (PMID 29734366, 2018). "Therefore, the increased Brd3 interaction with IRF3/p300 complex upon viral infection we detected here might possibly correlated with the acetylation status of either IRF3 or p300 (or both)." (PMID 28045112, 2017). "Indeed, IRF3 plays an important role in the innate immune response to viral infection." (PMID 25759027, 2015). "Therefore, the interaction of endogenous Pin1 with SUMOylated PMLIV and its recruitment in PML NBs could alter Pin1-induced downregulation of activated IRF3 thus resulting in a higher amount of phosphorylated IRF3 during viral infection." (PMID 24586174, 2014). "HSCARG also interacted with Ikappa-B kinase epsilon (IKKε) after viral infection and impaired the association between TRAF3 and IKKε, which further decreased the phosphorylation of IKKε and interferon response factor 3 (IRF3), thus suppressed the dimerization and nuclear translocation of IRF3." (PMID 24763515, 2014). "In response to viral infections, the CARD domain of IFIH1 receptor associate with the CARD-containing adaptor molecule known as IPS-1 (IFN promoter stimulator-1), activating the transcription factors NF-κB and IRF-3, which then cooperate in induction of antiviral IFN-I response." (PMID 24386202, 2013). "Upon viral infection the ubiquitously expressed protein IRF-3 is activated through phosphorylation, leading to its homodimerization and translocation to the nucleus where, in addition to activating transcription of IFN, a number of other antiviral genes that may induce apoptosis are activated." (PMID 24100888, 2013). "As both IRF3 and IRF7 exert their transcriptional effect by interacting with CBP/p300 and other HAT activities, these coactivators might participate to the recruitment of HDAC activities that target chromatin-associated histones during viral infection." (PMID 22685561, 2012). "Similarly, in the absence of IRF3, mice are more susceptible to virus infection due to a 20–50 fold reduction in type I IFN expression." (PMID 22363706, 2012). "Thus, the specific mechanisms by which IRF-3 modulates viral infection remain controversial." (PMID 17676997, 2007). "The IKBKE protein is a key adapter in antiviral innate immune signaling, phosphorylating IRF3 and promoting the production of type I IFN to combat viral infections." (PMID 41319264, 2026). "The mechanism of action involves viral infection upregulating hnRNP D, which interacts with the key transcription factor IRF3, disrupting the TBK1-IRF3 signaling axis." (PMID 42126233, 2026). "The results revealed that both viral infection and overexpression of SVCV-P significantly decreased IRF3 levels in the nucleus, indicating that SVCV-P inhibits IRF3 nuclear translocation." (PMID 41363845, 2026). "Virus infection leads to type 1 IFN production through inducing the dimerization and subsequent nuclear translocation of IRF3." (PMID 41931065, 2026). "This protein is activated by TLRs during the immune response and regulates gene expression in response to cytokines, stress, and bacterial or viral infections, as well as notably the IFN regulatory factors (IRFs, particularly IRF3, IRF4, and IRF8)." (PMID 40665467, 2025).
viral infection (continued). "Viral infection activates the TLR-3 signaling pathway and the phosphorylation of IRF-3, which leads to its translocation to the nucleus." (PMID 40431442, 2025). "After HeLa cells are infected with the wild-type measles virus, ADAR1 can effectively suppress the viral infection by enhancing cell apoptosis, activating PKR and IRF3, inducing IFN-β and suppressing the stress granule response." (PMID 41488000, 2025). "Viral infection induces the expression of canonical type I IFNs, such as IFN-β, via IRF3 and IRF7 transcription factors." (PMID 39668245, 2025). "IRF3 is the downstream effector of TBK1 and plays a crucial role in the immune defense against viral infection." (PMID 40036222, 2025). "It exhibits unique features that have evolved to adapt to virus infections, such as lower NLRP3 production, greater expression of IFNα1, and greater phosphorylation of IRF3." (PMID 40108733, 2025). "NLRX1 negatively regulates MAVS-mediated IRF3 activation and type I IFN induction during viral infection." (PMID 41463370, 2025). "In conclusion, we have clarified that RNF149 expression is induced upon viral infection, and RNF149 regulates the IRF3 degradation." (PMID 40245000, 2025). "In human THP-1 cells, ferrous iron potently attenuated the viral infection-induced expression of IFN-β and the activation of IRF3, TBK1, and STAT1, resulting in the enhancement of viral replication." (PMID 40595467, 2025). "Viral protein US3 has been shown to phosphorylate various crucial regulators, such as RIG-I, β-catenin, and IRF3, to suppress IFN-β production and promote viral infection." (PMID 39747662, 2025). "This includes IRF3 (interferon regulatory factor 3), the primary early regulatory factor responsible for inducing IFN-1 during viral infection, which positively regulates apoptosis and inhibits NF-kB translocation." (PMID 40877796, 2025). "Full activation of NF-κB, IRF3, and AP-1 binding with IFN-β enhancer is needed for high levels of type I IFN expression, contributing to an essential defence against viral infection." (PMID 40500801, 2025). "Upon virus-infection, additional CHs are established proximal to C/I-III members, and, frequently, are (co)-occupied by IRF3, p65, and CBP, consistent with the transcriptional stimulation of these vruDEGs upon virus infection." (PMID 40131776, 2025). "The TBK1/IKKε complex is a key adapter in antiviral innate immune signaling, with both proteins phosphorylating IRF3 to promote IFN-I production and combat viral infections." (PMID 40548751, 2025). "SIRT7 decreases IRF3/IRF7 phosphorylation to block the interaction between tbk1 and IRF3/IRF7, resulting in the suppression of antiviral responses, disruption of SIRT7 increases the survival rate of carp during virus infection." (PMID 40636259, 2025). "Paradoxically, Thr50 phosphorylation can also enhance viral infection by facilitating RACK1 interaction with interferon transcriptional factor IRF3, suppressing IRF3 phosphorylation and subsequent interferon synthesis." (PMID 41373878, 2025). "Under viral infection conditions, MAVS is known to promote polymerization through CARD-CARD interactions, which recruit IRF3 by IKK-ε and TBK1, leading to the activation of IFN-β." (PMID 40944942, 2025). "Early studies reported that TRAF3 activates TBK1 upon virus infection and that TBK1 and IRF3 then form a complex." (PMID 40234418, 2025). "In the context of viral infection, HDAC1 plays a crucial role in enabling transcriptional activation of ISGs through IRF3 (35, –, 37)." (PMID 39927774, 2025). "In agreement with our results in iBMDMs, we observed significantly higher levels of phospho-IRF3 and cleaved CASP3 in tfeb tfe3 DKO in response to viral infection, as well as reduced cell viability." (PMID 40195022, 2025). "Taken together, these results indicate that TXNIP negatively regulates MAVS aggregation during viral infection, thereby attenuating activation of downstream signaling pathways such as TBK1 and IRF3." (PMID 40628121, 2025).
viral infection (continued). "Within the IRF family of transcription factors, IRF3, IRF5, and IRF7 have well-described roles in mediating antiviral and inflammatory responses downstream of diverse viral infections." (PMID 40493408, 2025). "In resting cells, IRF3 resides in the cytoplasm, but becomes phosphorylated by TBK1 and IKKε upon viral infection." (PMID 40700455, 2025). "During viral infection, PTEN dephosphorylates the Serine 96 residue of IRF-3 and promotes IRF-3 nuclear translocation to activate the transcription of the genes related to IFN signalling pathways." (PMID 40793828, 2025). "In contrast, the administration of GUGG prevented the endogenous interaction of FXR and IRF3 during VSV infection, indicating that enhanced FXR interaction with IRF3 relies on FXR activation upon viral infection." (PMID 39220861, 2024). "For instance, in the context of viral infections, NBR1 plays a role in reducing the production of type I interferon by degrading IRF3 through autophagy, thereby assisting in the attenuation of the inflammatory response." (PMID 38169523, 2024). "The expression of ISGs typically follows prominent activation of IRF3 and IRF-7 during viral infections." (PMID 39640591, 2024). "Subsequently, the TBK1-mediated IRF3 axis or the IKKs-mediated NF-κB axis is employed, resulting in the production of IFN-I, pro-inflammatory cytokines, and chemokines in response to viral infection." (PMID 39058724, 2024). "This complex phosphorylates and activates IRF3 and IRF7, which in turn initiate the transcription of a variety of cytokines to resist virus infection." (PMID 39211800, 2024). "Here, we use poxviruses engineered to lack poxin to investigate how virus infection triggers the activation of STING and its downstream transcription factor interferon-responsive factor 3 (IRF3)." (PMID 39431915, 2024). "Subsequently, MAVS connects RIG-I/MDA5 to IKK and TBK1/IKKε, activating IRF3 and NFκB—the two crucial components of the pathway that induce IFN in response to viral infection." (PMID 39335111, 2024). "A Viral infection not only upregulates PRMT6 protein levels, but also promotes the binding between PRMT6 and IRF3 and dampens the interaction between IRF3 and TBK1." (PMID 38257273, 2024). "Activation of type I interferon is regulated by the IRF3 transcription factor, which undergoes phosphorylation-dependent activation by the upstream kinase, TBK1, during viral infection." (PMID 38495890, 2024). "However, as an important antiviral key signaling molecule, viral infection may keep modest IRF3 protein expression through protein translation and post-translational modifications such as the ubiquitin-proteasome pathway and caspase activity cleavage to avoid excessive immunity." (PMID 39362857, 2024). "Upon virus infection, IRF3, as a critical transcription factor in the IFN induction pathway, can be phosphorylated and activated by TBK1, and then phosphorylated IRF3 translocates from the cytoplasm into the nucleus, eliciting the expression of antiviral IFNs." (PMID 38285487, 2024). "As such, PR8 infection specifically induces transcription factor RUNX1, which blocks the expression of IRF3 and STAT1 to attenuate the production of IFN-β and ISGs to facilitate viral infection in A549 cells." (PMID 38817972, 2024). "It was found that the expression levels of EccGAS, EcSTING, IRF3/IRF7, IFNc, and ISGs were upregulated after viral infection, indicating a potential anti-RNA virus role of EccGAS-mediated IFN signaling in response to NNV infection." (PMID 38888343, 2024). "During viral infection, activation of the TBK1/STING/IRF3 signaling cascade leads to the expression of IFN-I." (PMID 39345209, 2024). "After viral infection, these receptors recruit downstream molecules, including MAVS, TBK1, or RIP2 to activate IRF3, a common molecule in all innate immune signaling pathways." (PMID 38516932, 2024).
viral infection (continued). "Upon viral infection, METTL3 enhances the nuclear export and translation of antiviral signaling molecule mRNAs, such as IRF3, and promotes the induction of IFN-β and inflammatory cytokines against viral infection." (PMID 38957616, 2024). "During viral infection, MyD88 is upregulated, and the interaction of MyD88 through its TIR domain with IRF-3/IRF-7 sequesters IRF-3/IRF-7." (PMID 39125989, 2024). "IRF-3 is expressed in many types of cells, playing a unique and important role in the induction of IFN-β in response to viral infection." (PMID 39459934, 2024). "Similar to NF-κB, the activation of IRF family members such as IRF3 and IRF7 are crucial for IFN responses to virus infection." (PMID 38891876, 2024). "During the early stages of viral infection, it is possible that the host gene MORC3 interacts with nuclear IRF3 to potentially facilitate the degradation of phosphorylated IRF3." (PMID 38150467, 2023). "Upon viral infection, RLRs induce mitochondrial antiviral signaling protein (MAVS) and Interferon regulatory factor 3 (IRF3), and MAVS is attached to the mitochondrial membrane." (PMID 36851739, 2023). "In viral infections, inhibiting the expression of miR-369-3p dramatically reduces the expression of antiviral response genes, including CCL3, CCL5, CTSS, CXCL11, and IRF3." (PMID 37509488, 2023). "It has a physiological role in innate immune system activation, notably in response to viral infection, by triggering IRF3 (Interferon Regulatory Factor 3) and NF-κB signaling, thereby triggering an inflammatory response." (PMID 37414800, 2023). "We further demonstrated that Bmp4 promotes the phosphorylation of Tbk1 and Irf3 through the p38 MAPK pathway, thereby inducing the production of type I IFNs in response to virus infection." (PMID 37833891, 2023). "Viral infections lead to synthesis of IFN and IRF3, and these proteins lead to transcription of OASL." (PMID 37922302, 2023). "cGAS/STING pathway plays a central role in immune defense against tumors and viral infections, where TANK-binding kinase 1 (TBK1) recruitment to STING further activates both NF-κB and interferon regulatory factor 3 (IRF3)." (PMID 38283361, 2023). "The increase in sterols then participates the activation of IRF3 and IRF7 and triggers the fish’s innate immunological response to the virus infection." (PMID 36901854, 2023). "This included genes of IRF3-mediated induction of type I IFN and SMAD2/3 signaling, which are essential pathways in regulating type 1 interferons during bacterial and viral infections." (PMID 37664632, 2023). "ZAP can be activated by viral infection due to the presence of binding sites for the signal transducer and activator of transcription (STAT) and Interferon Regulatory Factor 3 (IRF3) in its promoter." (PMID 38133344, 2023). "It does so by recruiting the VISA complex, which facilitates the activation of transcription factors IRF3 and NF-κB, thereby activating the IFN-β promoter induced by viral infection." (PMID 38200810, 2023). "It is generally agreed that vIRF1 interacts with IRF3 to disrupt the formation of IRF3-CBP/p300 complexes, resulting in the suppression of the early response of IFN to virus infection." (PMID 37023208, 2023). "Viperin can be induced by IRF-3 and IRF-7 mediated production of IFNs and combat different virus infection in myeloid DCs." (PMID 36315280, 2023). "ISIR activates the Interferon Regulatory Factor-3 (IRF3) and strengthens the interferon response to viral infections." (PMID 37048060, 2023). "Upon viral infection, BLK undergoes Y309 autophosphorylation and directly phosphorylates IRF3 at Y107, together with TBK1-induced IRF3 S386 and S396 phosphorylation, to achieve sufficient IRF3 activation and elicit robust downstream antiviral responses." (PMID 37871014, 2023). "Apart from viral infection, PRMT-mediated arginine methylation also enhances IFN-β production in the TLR4/IRF3 signaling pathway." (PMID 37928266, 2023).
viral infection (continued). "Given the presence of both NLS and NES in IRF3, its predominant cytoplasmic localisation suggested constitutive activities of NES before virus infection, nuclear exports dominated nuclear imports." (PMID 36817435, 2023). "TBK1 phosphorylates Interferon regulatory factor 3 (IRF3), which mediates the expression of Interferon (IFN)-β and promotes type I IFN responses following viral infection." (PMID 36552877, 2022). "Upon virus infection, BRD3 promotes the recruitment of the IRF3/p300 complex to the promoter of Ifnb1, leading to the transcription and production of type I interferon." (PMID 35743279, 2022). "The host-response to viral infection, via a type-I IFN response, the first line of antiviral defense, requires IRF3 activities." (PMID 36507301, 2022). "IRF3 and IRF7 are the master transcription factors driving IFN production in response to viral infection." (PMID 36172355, 2022). "Interferon regulatory factor 3 (IRF3), a transcriptional factor, plays a key role in innate responses against viral infection." (PMID 36405960, 2022). "Upon viral infection, cellular TBK1- and IKKi-mediated Ser385 and Ser386 phosphorylation of IRF3 and the Ser/Thr cluster between amino acids 396 and 405 of IRF3 leads to its conformational change and activation." (PMID 35196784, 2022). "IRFs, especially IRF3 and IRF7, are members of the interferon regulatory factor family, which are closely related to the expression of interferon genes during virus infection." (PMID 35457287, 2022). "These kinases are considered master regulators of inflammation and innate immunity via control of the transcription factors IRF3, IRF7 and NF-κB during viral infection." (PMID 36311756, 2022). "In viral infection, TLR3 recognizes dsRNA and, through TRIF, transmits signals to activate the transcription factor IRF3." (PMID 35563088, 2022). "IRF3 and IRF7 are two key transcription factors that modulate type I IFN expression upon viral infection." (PMID 35215986, 2022). "Previous work also suggested YAP interacts with IRF3, preventing its dimerization and nuclear translocation, which further reduces the production of IFN-β and ISGs in response to virus infection." (PMID 35503798, 2022). "Previous studies have demonstrated that RNF5 inhibits the activation of IRF3 and NF-κB signaling pathways by mediating the ubiquitination and degradation of STING triggered by viral infection to avoid excessive antiviral responses." (PMID 36270989, 2022). "In response to viral infection, MAVS, a membrane-bound protein, transmits signals from RIG-I to downstream signaling molecules via the transcription factors NF-B, IRF3, and IRF7 to create inflammatory cytokines such as IFN-beta." (PMID 36776376, 2022). "Thus, although our RLR or cGAS findings remain to be confirmed and extended with analyses of kinase-deficient Pim1, they tentatively suggest that targeting the kinase-independent interaction between Pim1 and the IRF3 signaling complex could help control viral infections." (PMID 36446848, 2022). "These ISRE elements along with transcription factors in IFN signalling like IRF3, regulate ISG15 expression in response to IFN or viral infection." (PMID 36419602, 2022). "Upon viral infections, IκB kinase-related kinases TBK1 and IKKε activate the transcription factors such as IRF3 and IRF7, resulting in IFN-β production." (PMID 39290965, 2022). "IRF7 is the main regulator of type I interferon (IFN) expression, which can form dimers with IRF3, and type I IFN expression was impaired in Irf7−/−plasmacytoid dendritic cell precursors (pDCs) or mouse embryonic fibroblast (MEFs) upon virus infection." (PMID 36618529, 2022). "In this study, we confirmed that lncRNA IRF1-AS enhanced the phosphorylation of IRF3, promoted the production of IFN-β and ISGs and significantly inhibited viral infection." (PMID 36307867, 2022).